STC1 (stanniocalcin 1)
Diseases named in the same sentence as STC1 in open-access papers (continued):
Sharing a sentence is not in itself a finding about the gene and the disease.
gastric cancer (16 papers, 2011 to 2025). A primary or metastatic malignant neoplasm involving the stomach. "STC1 also promotes metastasis of gastric cancer, Fang et al48 found out that a high STC1 expression level in GC tissues was associated with more lymph metastasis in GC patients (P = .029)." (PMID 32468698, 2020). "The study assessed the expression of STC1, and its potential as an immunotherapy target in gastric cancer (GC)." (PMID 40741411, 2025). "Recent studies have shown that STC-1 promotes tumor angiogenesis, glycolysis, and metastasis in several malignancies, including breast, lung, and gastric cancers." (PMID 39071498, 2024). "Meanwhile, in gastric cancer, STC1 fosters tumor angiogenesis through the upregulation of VEGF, indicating its role in supporting tumor growth and metastasis by promoting new blood vessel formation." (PMID 39668832, 2024). "In this study, we for the first time showed that STC-1 enhances the expression of VEGF in gastric cancer cells and promotes tumor growth through enhancing tumor angiogenesis." (PMID 21672207, 2011). "STC-1 promotes tumor angiogenesis by upregulating VEGF in gastric cancer cells." (PMID 39071498, 2024). "It suggested that ADAM12, EDNRA, and STC1 had high value in the diagnosis of gastric cancer." (PMID 34663825, 2021). "Our previous study found that STC-1 gene could be activated in human gastric cancer BGC823 cells with over-expressed midkine." (PMID 21672207, 2011). "Stanniocalcin-1(STC-1) is up-regulated in several cancers including gastric cancer." (PMID 21672207, 2011). "It is well known that VEGF is one of the most common promoters of angiogenesis, as an angiogenetic factor, so we investigated whether STC-1 could regulate the expression of VEGF in the gastric cancer cell." (PMID 21672207, 2011). "We found that ectopic-expression of STC-1 could promote VEGF production in the gastric cancer cell." (PMID 21672207, 2011). "By analyzing the co-expression correlation between CPT1A, IL-8, CXCL5, STC1 and CD44 in stomach cancer tissues through TCGA database, we found that these genes except CXCL5 were positively correlated with CD44 and were positively associated with at least one MSC markers (ENG, THY1, NT5E)." (PMID 37158903, 2023).
glioma (16 papers, 2017 to 2025). A benign or malignant brain and spinal cord tumor that arises from glial cells (astrocytes, oligodendrocytes, ependymal cells). "Among the transcripts down-regulated in DUSP8-GFP GSC#1 and up-regulated in sh-DUSP8-GFP GSC#1 we found stanniocalcin-1 (STC1), a secreted glycoprotein associated with poor prognosis, glioma grade, and resistance to TMZ therapy." (PMID 41029387, 2025). "Subsequent studies have shown that STC1 expression increases in gliomas and is associated with tumor development and progression." (PMID 34394104, 2021). "The results indicated that the expression of STC1 was increased in glioma tissues along with the pathological characteristics." (PMID 41020346, 2025). "Then, Kaplan–Meier survival suggested that glioma patients with higher expression of STC1 exhibited worse outcomes (all p < 0.05)." (PMID 41020346, 2025). "Using publicly available datasets of scRNA seq of glioblastoma, both CALR and STC1 expression are increased as a function of glioma grade." (PMID 38786045, 2024). "The two most significantly regulated genes in both categories were stanniocalcin 1 (Stc1), a gene up-regulated in gliomas and WD repeat and FYVE domain-containing protein 1 (Wdfy1), a gene expressed in neural progenitors." (PMID 34394104, 2021). "Stanniocalcin 1 was reported to be overexpressed in glioma, and its upregulation in glioma patients predicted a poor prognosis." (PMID 34976054, 2021). "In contrast to our findings, high expression of STC-1 has been shown to correlate with an advanced tumor grade in glioma and ovarian serous carcinomas, suggesting pleiotropic effects of STC-1 that depend on the type of cancer." (PMID 34650342, 2021). "The hypoxia-induced glioma secretome analysis by LC-MS/MS reported that stanniocalcin 1 (STC1) and stanniocalcin 2 (STC2) have a role in the induction of glioma cell migration in a hypoxia-dependent manner." (PMID 31405033, 2019). "Another target of miR‐4484, STC1, also exhibited relatively higher expression in high‐grade gliomas as compared to low‐grade samples." (PMID 28378523, 2017). "STC1 was upregulated in GBM patients compared with the low‐grade glioma patients." (PMID 41020346, 2025). "STC1 is a prognostic marker in gliomas (p = 0.03), agreeing with a previous analysis." (PMID 38786045, 2024). "Furthermore, STC1 can activate the Notch1 signaling pathway as an atypical ligand of the Notch1 receptor in glioma." (PMID 37004088, 2023). "STC1 was a direct target of miR‐1205 and miR‐382 in glioma cells." (PMID 33543830, 2021). "Besides, STC1 could affect the metastasis of glioma through the TGF-β/SMAD4 pathway, and affect the metastasis of liver cancer through the JNK pathway." (PMID 33644060, 2021). "We analyzed the data from the TCGA database using the same methodology and also found that the expression of STC1 was higher in GBM compared with the other gliomas, as well as glioma patients with higher expression of STC1 had poor prognoses (all p < 0.05)." (PMID 41020346, 2025). "In this review, we examined the role of phagocytic cell death in gliomas and strategies to modulate the balance between “don’t-eat-me” CD47/SIRPα and “eat-me” CALR/STC1 axes for therapeutic benefits." (PMID 38786045, 2024). "STC1 and NKX3-1 have been demonstrated to enhance glioma cell proliferation, stemness, migration, and invasion." (PMID 32528873, 2020). "Luo and coworkers have recently shown that STC1 levels directly correlate with those of matrix metalloproteinases (MMP)-2, MMP9, and vimentin in gliomas, and these authors hypothesized that STC1 augments the invasive capacities of glioma cells." (PMID 34394104, 2021). "Furthermore, the TCGA and CCLE data showed that STC1, HMOX1 and TGFB1 were obviously up‐regulated in most glioma cells." (PMID 31282108, 2019).
cervical carcinoma (15 papers, 2013 to 2025). A carcinoma arising from either the exocervical squamous epithelium or the endocervical glandular epithelium. "In conclusion, our studies confirmed that the expression of STC1 in cervical cancer is associated with tumor stage." (PMID 28545028, 2017). "The loss of function of STC1, which inhibit the growth and invasion of tumor cells, might lead to tumor progression in cervical cancer." (PMID 23382863, 2013). "In cervical cancer, the low expression of STC1 might cause tumor development." (PMID 23382863, 2013). "Research has shown that overexpression of STC1 promoted NF‐κB phospho‐P65 (Ser536), thereby inducing apoptosis in cervical cancer cells, revealing STC1 as a potential therapeutic target for cervical cancer." (PMID 41020346, 2025). "Consistent with our findings, the association of reduced STC-1 expression with the worse clinicopathological outcome has also been found in cervical cancer, suggesting a role for STC-1 as a pro-apoptotic protein." (PMID 34650342, 2021). "On the contrary, STC1 was reported to inhibit cell proliferation in cervical cancer cells through NF-κB p65 activation." (PMID 32155780, 2020). "Our results offer the first mechanism that explains the link between STC1 and cell apoptosis in cervical cancer." (PMID 28545028, 2017). "Phospho-protein profiling and Western blotting results showed the expression of NF-κB related phosphorylation sites including NF-κB P65 (Ser536), IκBα, IKKβ, PI3K, and AKT was altered in STC1-overexpressed cervical cancer cells." (PMID 28545028, 2017). "The results showed that STC1 was mainly localized in the nucleus of cervical cancer cells and was lower expression in cervical tumor tissues than normal tissues." (PMID 28545028, 2017). "To explore the precise role of STC1 in cervical cancer diagnosis and prognosis, we examined the expression of STC1 in cervical cancer tissues and normal tissues by immunohistochemistry." (PMID 28545028, 2017). "Our findings provide a novel insight for STC1 as a target or biomarker in the therapy and prevention of cervical cancer." (PMID 28545028, 2017). "In our studies, we found overexpression of STC1 promoted cell apoptosis while silencing of STC1 promoted cell growth of cervical cancer." (PMID 28545028, 2017). "Our results suggest that NF-κB P65 phosphorylation at Ser536 is involved in anti-apoptotic effect of STC1 in cervical cancer cells." (PMID 28545028, 2017). "Our previous studies revealed that STC1 inhibited cell proliferation and invasion of cervical cancer cells through NF-κB P65 activation, but the mechanism is poorly understood." (PMID 28545028, 2017). "Our previous studies have shown that STC1 is on the decrease in cervical cancer cells for the first time, and that it suppresses cellular multiplication and metastasis of cervical cancer cells likely through NF-κB P65 protein." (PMID 28545028, 2017). "In this study, we reported a molecular mechanism of STC1 regulating cell apoptosis of cervical cancer, which was through regulating cell apoptosis via NF-κB phospho-P65 (Ser536) by PI3K/AKT, IκBα and IKK signaling." (PMID 28545028, 2017). "The results of immunohistochemistry for the cervical cancer microarray showed that the antigens of STC1 and phospho-PI3K were weakly detected in tumor tissues (p=0.008 and p=0.049, respectively), and the P65 antigen was too weak to be detected." (PMID 28545028, 2017). "Yet, the specific phosphorylation site of NF-κB P65 that is involved in the anti-apoptotic effect of STC1 in cervical cancer cells is unclear." (PMID 28545028, 2017). "The elevated STC1 expression decreased tumor progression, and accordingly the sensitivity of the cervical cancer cells with elevated STC1 expression to the chemotherapy drug increased." (PMID 23382863, 2013). "We also found that STC1 overexpression inhibited cell proliferation and invasion of cervical cancer cells." (PMID 23382863, 2013).
cervical carcinoma (continued). "In this study, we found that STC1 inhibited cell proliferation and invasion of cervical cancer cells." (PMID 23382863, 2013). "The expression level of STC1 mRNA in cervical cancer tissues was decreased compared with the adjacent normal ones." (PMID 23382863, 2013). "Here, we found that STC1 is down-regulated in Clinical tissues of cervical cancer compared to the adjacent normal cervical tissues (15 cases)." (PMID 23382863, 2013). "Then, immunohistochemistry analysis revealed that the protein level of STC1 was low in tumor tissues, and while increased in adjacent normal tissues, indicating its potential role in the progression of cervical cancer." (PMID 23382863, 2013). "Subsequently, we found that STC1 low expression promoted cell growth, migration and invasion after the down-regulation of STC1 by RNA interference in cervical cancer cells." (PMID 23382863, 2013). "STC1 is down-regulated in Clinical tissues of cervical cancer, which indicated STC1 is involved in the progression of cervical cancer." (PMID 23382863, 2013). "Further, we showed that NF-κB p65 protein directly bound to STC1 promoter and activated the expression of STC1 in cervical cancer cells." (PMID 23382863, 2013). "To explore the role of STC1 in cervical cancer, we first examined the mRNA expression level in 15 pairs of matched cervical tissues by RT-PCR." (PMID 23382863, 2013). "We showed that NF-κB p65 protein directly bound to STC1 promoter and regulated the expression of STC1 in cervical cancer cells." (PMID 23382863, 2013). "Further, we also found that STC1 overexpression inhibited cell proliferation and invasion of cervical cancer cells." (PMID 23382863, 2013). "Subsequently, the expression of STC1 was knocked down by RNA interference in cervical cancer CaSki cells and the low expression promoted cell growth, migration and invasion." (PMID 23382863, 2013). "Additionally, MEG3 induced apoptosis in cervical carcinoma cells through endoplasmic reticulum stress and the miR-7-5p/STC1 axis." (PMID 40242248, 2025). "demonstrate that STC1-dependent immune escape from macrophage phagocytosis can be suppressed by the inhibition of competitive interaction between LNMAS and HMGB1, resulting in the abrogation of TWIST1 and STC1 chromatin accessibility, thereby suppressing cervical cancer lymph node metastasis." (PMID 38144565, 2023). "STC1 regulates cellular apoptosis in cervical cancer via the NF-κB pathway." (PMID 35607443, 2022). "In addition to the numerous cellular functions, STC-1 has also been reported to be involved in various human cancers, including breast, ovarian, and cervical cancers, by regulating cellular proliferation, invasion, and metastasis." (PMID 34650342, 2021). "As Guo et al49 reported, NF‐κB p65 protein directly bound to STC1 promoter and activated the expression of STC1 in cervical cancer cells, thus the decreased non‐phosphorylated p65 protein level then leads to the reduced expression of STC1, the phenomenon we observed in tumour tissues." (PMID 32468698, 2020). "Our previous studies have shown that NF-κB P65 protein may directly bind to the promoter of STC1 and activate the expression of STC1 in cervical cancer cells." (PMID 28545028, 2017). "Whether these kinases involved in phosphorylation of Ser536 with STC1 have a role in cervical cancer cells needs to be further analyzed." (PMID 28545028, 2017). "However, the role and molecular mechanism of STC1 in the cell apoptosis of cervical cancer remain to be fully elucidated." (PMID 28545028, 2017). "So we detected the regulatory effect of PI3K/AKT, IκBα and IKK signaling on the expression of apoptosis related genes Bax and Bcl-2, in order to make sure whether STC1 works through the PI3K/AKT signaling to regulate cell apoptosis of cervical cancer cells." (PMID 28545028, 2017). "We found that STC1 was down-regulated in Clinical tissues of cervical cancer." (PMID 23382863, 2013).
cervical carcinoma (continued). "In this study, we examined the role of STC1 gene expression in human cervical cancer." (PMID 23382863, 2013). "Our results suggest that enhancing the expression of STC1 should be a good strategy to inhibit tumor proliferation and invasion and also might be a feasible combined treatment with chemotherapeutic drugs in cervical cancer." (PMID 23382863, 2013). "Additionally, STC1 level was decreased in cervical cancer, especial in stage II and III." (PMID 28545028, 2017). "In cervical cancer tissues and cell lines, the expression of MEG3 and STC1 is diminished, while the expression levels of miR-7-5p are elevated." (PMID 40242248, 2025). "Trichostatin A suppresses cervical cancer cell proliferation and induces apoptosis and autophagy through regulation of the PRMT5/STC1/TRPV6/JNK axis." (PMID 34440894, 2021). "TSA suppresses cervical cancer cell proliferation and induces autophagic cell death through the regulation of the PRMT5/STC1/TRPV6/JNK axis." (PMID 34575981, 2021). "Moreover, PI3K inhibitor LY294002, AKT-shRNA and IκBα-shRNA could decrease the protein content of phospho-P65 (Ser536), phospho-IκBα, phospho-AKT and phospho-IKKβ while increasing the level of P65 compared to STC1 overexpression groups in cervical cancer cells." (PMID 28545028, 2017). "In cervical cancer cells, TSA (1 μM) induces autophagy by significantly suppressing protein arginine methyltransferase 5 (PRMT5) and transient receptor potential cation channel, subfamily V, member 6 (TRPV6) levels and enhancing stanniocalcin 1 (STC1) and JNK levels." (PMID 34575981, 2021). "To investigate whether NF-κB was involved in the pro-apoptotic effect of STC1 or not in cervical cancer, we analyzed Phospho-protein profiling in CaSki/STC1 cells and CaSki/NC cells via phospho-protein antibody array designed for NF-κB signaling pathway." (PMID 28545028, 2017).
glioblastoma (11 papers, 2014 to 2025). The most malignant astrocytic tumor (WHO grade IV). "We found that downregulation of STC1 expression reduced the tumorigenesis of the glioblastoma cells." (PMID 41020346, 2025). "Mechanistically, STC1 maintains glioblastoma “stemness” through the NOTCH1-SOX pathway and enhances tumorigenesis in vivo." (PMID 38786045, 2024). "STC1 enhances the stemness characteristics of glioblastoma cells by activating the NOTCH1-SOX2 signaling pathway." (PMID 39103836, 2024). "The migration and invasion of glioblastoma cells are partially regulated by STC1 through the TGF-β/SMAD4 signaling pathways." (PMID 38786045, 2024). "has demonstrated that overexpression of STC1 augments the stem-cell like properties of glioblastoma cells by increasing the NOTCH-SOX2 signaling pathway." (PMID 34394104, 2021). "In glioblastoma, in vitro experiments showed that STC1 could regulate glioblastoma invasion and metastasis through the TGF-β/Smad 4 signaling pathway." (PMID 34663825, 2021). "More recently, stanniocalcin-1 (STC-1), a microRNA-regulated secreted glycoprotein with physiological functions in autocrine-paracrine signalling, has been recognised as a metastasis-promoting factor in various cancers, including glioblastoma, by activating PI3K/AKT and JNK signalling pathways." (PMID 41008823, 2025). "STC1 was found to be highly expressed in GBM cells, enhancing the stem-like features of glioblastoma cells." (PMID 38159261, 2023). "These include previously identified HIF-1 target genes such as ANKRD37, STC-2, and STC-1, as well as COL5A1 induced by hypoxia in the ventricle, ZNF395 regulated by hypoxia in glioblastoma, and TMEM45 in hematopoietic stem cells." (PMID 25122487, 2014). "In glioblastoma (GBM), available studies indicate that STC1 accounts for the invasion steps of GBM." (PMID 35927233, 2022).
colon cancer (10 papers, 2011 to 2025). "Previous studies have proved that STC-1 is highly expressed in tumor vasculature in breast adenocarcinomas and colon cancers." (PMID 21672207, 2011). "In colon cancer cell lines, silencing of stanniocalcin 1 (STC1) reverses the tumor-promoting effects of miR-101 down-regulation, and overexpression of miR-101 generates anti-tumor effects by targeting the cAMP-responsive element binding protein 1 (CREB1) and Notch signaling pathway." (PMID 36497343, 2022). "Hence, our results revealed MIAT/miR-532/STC1 axis plays a crucial role in the occurrence, development, and prognosis of colon cancer." (PMID 35607443, 2022). "CAF-derived MMPs can promote ECM remodeling and tumor cell invasion, and in an orthotopic model of colon cancer, CAFs promote formation of distal metastases through secretion of the glycoprotein stanniocalcin 1 (STC1) which regulates intravasation of the tumor cells." (PMID 28883015, 2017). "In colon cancers, STC-1 was highly expressed during angiogenesis and the increased expression of STC-1 may be contributed primarily by the tumor vasculature." (PMID 21672207, 2011). "In colon cancer, the lncRNA-MALAT1/miR-101-3p/STC1 axis can promote the development of the tumor." (PMID 35607443, 2022). "STC1 and ARL4C were found to be significantly upregulated in colon cancers." (PMID 35607443, 2022). "The relative expression of STC1 and ARL4C showed significant upregulation in colon tumor tissues." (PMID 35607443, 2022).